ASPNAT (aspartate N-acetyltransferase)
Description:
Catalyzes the synthesis of N-acetylaspartate acid (NAA) from L-aspartate and acetyl-CoA. Promotes dopamine uptake by regulating TNF expression (By similarity). Attenuates methamphetamine-induced inhibition of dopamine uptake.
Synonyms: NAT8L; CML3; FLJ37478; Hcml3; Shati; NACED; NAT8-LIKE
Tractability: Antibody: UniProt predicts a signal peptide or a membrane-spanning region. PROTAC: ubiquitination databases record sites on it.
Gene: Protein-coding gene on chromosome 4 (2,059,327 to 2,069,089, forward strand). Ensembl gene ENSG00000185818.
Subcellular location: Cytoplasm; Microsome membrane; Mitochondrion membrane; Endoplasmic reticulum membrane
Subcellular location (Human Protein Atlas): Mitochondria
Pathways (Reactome):
Metabolism: Aspartate and asparagine metabolism
Gene Ontology:
Molecular function: L-aspartate N-acetyltransferase activity; protein binding; acyltransferase activity, transferring groups other than amino-acyl groups; N-acetyltransferase activity
Biological process: L-amino acid metabolic process
Cellular component: cytoplasm; mitochondrial membrane; endoplasmic reticulum membrane; mitochondrial matrix; mitochondrion
Genetic constraint (gnomAD): Loss-of-function variants: 6 observed, 13.87 expected, observed/expected ratio (o/e) 0.43, 90% interval 0.24 to 0.85. The synonymous counts are far from expectation, so gnomAD's model fits this gene poorly and the ratio says little. Missense variants: 265 observed, 310.61 expected, observed/expected ratio (o/e) 0.85, 90% interval 0.77 to 0.94. Synonymous variants: 210 observed, 147.8 expected, observed/expected ratio (o/e) 1.42, 90% interval 1.27 to 1.59.
Homologues: Orthologues: dog NAT8L (95% identical), rat Nat8l (94% identical), mouse Nat8l (94% identical), pig NAT8L (94% identical), chimpanzee NAT8L (82% identical), zebrafish nat8l (60% identical), tropical clawed frog nat8l (57% identical). Paralogues in human: NAT8 (24% identical), NAT14 (14% identical).
Diseases named in the same sentence as ASPNAT in open-access papers:
ASPNAT is named in the same sentence as 32 diseases in open-access papers, as found by Europe PMC text mining. Sharing a sentence is not in itself a finding about the gene and the disease. The quoted sentences say what the papers report.
brain tumors (2 papers, 2020 to 2021). "Apparently, the absence of NAA biosynthetic enzyme (aspartate N-acetyltransferase) in brain tumors is the main cause of NAA signal loss." (PMID 34884511, 2021).
cancer (9 papers, 2016 to 2025). A tumor composed of atypical neoplastic, often pleomorphic cells that invade other tissues. "Aspartate N-acetyltransferase (NAT8L), a NAA biosynthetic enzyme, was negatively associated with overall survival duration in CRC patients, as shown in the cancer genome atlas (TCGA)." (PMID 40727475, 2025).
brain disorder (1 paper, 2020). A disease affecting the brain or part of the brain. "Recently, aspartate N-acetyltransferase (NAT8L) has been identified as a candidate for a mechanism-based molecular target in treatment strategies against neurodegeneration concomitant with progressive brain disorders starting with degeneration of cholinergic neurons." (PMID 32545833, 2020).
ASPNAT also shares sentences with these, for which no sentence is quoted: tumor (6 papers); Canavan disease (4); Obesity (3); ovarian carcinoma (3); depression (2); lung carcinoma (2); melanoma (2); microcephaly (2); psychiatric disorder (2); adenocarcinoma (1); Alzheimer disease (1); Ataxia (1); convulsion (1); developmental delay (1); epilepsy (1); Hyperglycemia (1); Hypertension (1); leukodystrophy (1); lung adenocarcinoma (1); multiple sclerosis (1); neuroblastoma (1); Neurodegeneration (1); non-small cell lung carcinoma (1); ovarian tumours (1); pancreatic cancer (1); prostate tumor (1); schizophrenia (1); serous ovarian cancer (1); squamous cell carcinoma (1).